CDK1 (cyclin dependent kinase 1)
Diseases named in the same sentence as CDK1 in open-access papers (continued):
Sharing a sentence is not in itself a finding about the gene and the disease.
colon carcinoma (continued). "Similarly, in colon cancer, Micro RNA (miR)-490-3p can silence its target Cyclin-dependent kinase 1 (CDK1) by LLPS, leading to G1/S arrest and inhibiting cell proliferation." (PMID 37180732, 2023). "Thus, interaction between NOSTRIN and Cdk1 indicated a plausible mechanism behind increased inhibitory effect on Cdk1 and the proliferative potentials of colon cancer cells." (PMID 35642021, 2022). "Notably, experiments in the vemurafenib-resistant colon cancer sublines have shown stable activation of CDK1, signifying the role of CDK1 activation in stimulation of resistance to vemurafenib." (PMID 36266723, 2022). "Our result suggests that the decreased ubiquitination of CDK1 may be a potential mechanism of human colon cancer metastasis." (PMID 33014840, 2020). "Moreover, AJUBA is phosphorylated by CDK1, controls multiple cell cycle regulators, and promotes cell proliferation and tumorigenesis of colon cancer." (PMID 30690883, 2019). "Furthermore, we identified numerous CTS transcriptional signatures whose expression was significantly associated with prognosis in colon cancer, such as CEBPB, PPARGC1, STAT3, MTOR, BCL2, JAK2, and CDK1." (PMID 31186640, 2019). "According to that, we speculate that PADI3 may play its anti-tumor role via affect Hsp90, CKS1, CDK1 and p27kip1 expression in colon cancer." (PMID 31708688, 2019). "In order to evaluate whether glucocorticoid-GR signaling involves regulation through CDK1, particularly in metastatic colon cancer cells, we first used ChIP assay to determine the occupancy of GR at CDK1 gene promoter." (PMID 31375708, 2019). "Besides, sulforaphene treatment was also demonstrated to induce G2/M phase cell cycle arrest and apoptosis of colon cancer cells, concomitant with phosphorylation of CDK1 and CDC25B at inhibitory sites." (PMID 31889894, 2019). "It is found that CDK1 is remarkably downregulated in colon cancer cell lines." (PMID 30186855, 2018). "For example, Zeestraten and colleagues identified that Cdk1 but not Cdk2 can predict distant-metastasis-free survival and cause-specific survival in stage II colon cancer." (PMID 25511643, 2014). "The prognostic role of Cdk1 in colon cancer is still controversial." (PMID 25511643, 2014). "In addition, CDK1 is a marker of the clinical prognosis of colon cancer." (PMID 36247089, 2022). "However, Meyer and colleagues reported that the absence of Cdk1 expression by immunohistochemistry staining of tissue arrays was associated with significantly poor cancer-related 5-year survival in stage UICC II colon carcinoma." (PMID 25511643, 2014). "The CDK1/CDK2 inhibitors puruvanol A and roscovitine induce cell death in colon cancer cells and increase SSAT-1 levels." (PMID 37759783, 2023). "NFE2L3 functioned as an oncogene in colon cancer by suppressing the expression of DUX4, which functioned as a direct inhibitor of CDK1." (PMID 35059466, 2022). "In colon cancer, KCTD12/CDK1 fusion positive tumors have been shown to become vulnerable to vemurafenib via a coadjuvant treatment with adefovir dipivoxil." (PMID 33520715, 2020). "It is reported that the interaction between CDK1/cyclin B1 complex and ZNFX1 antisense RNA 1 (ZFAS1) leads to cell cycle progression and cell apoptosis suppression in the progression of colon cancer." (PMID 30186855, 2018). "Among them, ERK2, p38 or Cdk1 can phosphorylate TOPK at T9 and the positive feedback loop between TOPK and ERK2 seemed to contribute to transformation in colon cancer." (PMID 27016416, 2016). "The expression of cyclin A2, CDK1 and CDK2 in colon cancer HT-29 cells was decreased upon the knockdown of ANO1." (PMID 27732935, 2016).
colon carcinoma (continued). "The combination therapy tended to reduce the levels of phosphorylated CDK1 in SF-TY and colon cancer cell lines, although not significantly." (PMID 36765693, 2023). "Adefovir dipivoxil that interrupts the interaction between CDK1 and KCTD12 and induces cell cycle arrest at G2 could inhibit colon cancer cells proliferation and induce sensitivity to vemurafenib." (PMID 36266723, 2022). "Moreover, disruption of the interaction between CDK1 and KCTD12 using Adefovir dipivoxil has been shown to reduce in vivo tumorigenesis of colon cancer cells and induce vemurafenib sensitivity in xenografts." (PMID 36266723, 2022). "Cell cycle is a continuous system of biological processes, and several studies have elucidated that the lower level of CDK1 and CCNB1 in colon tumor cells slowed down the G2/M phase of the cell cycle, which owned to the retardation of cell cycle in the S phase." (PMID 33628185, 2020). "Interestingly, we found that many of the DEGs and their regulators were prognostic markers for colon cancer, including CEBPB, PPARGC1, STAT3, MTOR, BCL2, JAK2, and CDK1." (PMID 31186640, 2019). "Inhibition of Cdk1 and Cdk2 by 6,7,4′-trihydroxyisoflavone inhibited growth of HCT-116, a human colon cancer cell line, and JNJ-7706621, an inhibitor of Cdk1/cyclinB1 and aurora kinase effectively reduced growth of transplantable liver tumor in combination treatment with paclitaxel." (PMID 27385216, 2016). "The present study reveals a novel strategy for the use of the Cdk1 N/C ratio rather than the Cdk1 expression in the entire cancer cell for predicting prognosis of colon cancer patients." (PMID 25511643, 2014). "Thus, the dual inhibition of CDK1 and HSP90 inhibits colony formation by HCT116 colon cancer cells." (PMID 34686682, 2021). "Among the upstream regulators (TFs, kinases, and MMTRs) of the DEGs, the expression of STAT3, RPS6KA5, IKBKE, ERBB2, MTOR, and NFKB1 had a positive correlation with OS in colon cancer, while the expression of CDK1, CDK5, and BRD2 had a negative correlation with OS in colon cancer." (PMID 31186640, 2019). "These transcriptional signatures are mainly involved in immune regulation (CEBPB, STAT3, and JAK2), metabolism (PPARGC1 and MTOR), cell cycle (CDK1), and apoptosis (BCL2), suggesting that the deregulation of these pathways in CTS may contribute to the altered prognosis in colon cancer." (PMID 31186640, 2019). "However, in most of our experiments, 10 μM of NSC 95397 showed significant inhibitory activity on colon cancer cells without inhibiting the protein levels of Cdc25A and the Tyr-15 dephosphorylation of Cdk1." (PMID 29857489, 2018). "Interestingly, RACK1 has the opposite effect in colon cancer cells; RACK1 overexpression delays passage of HT-29 cells through G1 and mitotic checkpoints by suppressing Src-mediated Sam68 phosphorylation and maintaining the active state of CDK1-cyclinB." (PMID 28465488, 2017). "In this context, it is not surprising to observe that expression of CDK1, CDK2, and cyclin B2 (CCNB2), which have close functional interactions with an oncogenic protein CKS1B, was significantly increased in colon cancer samples in the TCGA data set." (PMID 31717435, 2019). "However, Meyer and colleagues revealed that patients with an ‘absent’ score for Cdk1 had poor cancer-related 5-year survival, indicating the absence of Cdk1 to be an independent prognostic marker in stage UICC II colon carcinoma." (PMID 25511643, 2014).
pancreatic cancer (67 papers, 2009 to 2025). "Previous studies showed that BA145, an analogue of boswellic acid, inhibited the proliferation of pancreatic cancer cells by arresting them at the G2/M phase, which is associated with decreased expression of cyclin B and CDK-1." (PMID 29970196, 2018). "In this study, we demonstrated that AR-42 inhibited growth of pancreatic cancer cells in vitro and in vivo, and caused cell cycle G2/M arrest by regulating expression levels of cyclin B1, cyclin B2, CDK1, and p21." (PMID 28829799, 2017). "The GEPIA2 online tool employed to analyze the OS and recurrence‐free survival (RFS) of 30 genes revealed four genes, including CAV1, TMEM43, IQGAP1, and CDK1, that were significantly correlated with pancreatic cancer risk based on their differential expression between tumor and normal tissues." (PMID 40539383, 2025). "In pancreatic cancer, CDK1 inhibition has been shown to overcome IFNG-mediated adaptive immune resistance." (PMID 40746552, 2025). "ZAG has also been shown to suppress the growth of oral and pancreatic cancer by downregulating cyclin-dependent kinase 1 gene and inducing mesenchymal-to-epithelial transdifferentiation, respectively." (PMID 38888911, 2024). "A phase I/II clinical trial of a CDK1 inhibitor plus gemcitabine for pancreatic cancer revealed that this regimen not only inhibited tumor growth but also eliminated resistance to gemcitabine." (PMID 36950551, 2023). "Here, we discovered that silencing CDK1 significantly inhibited a subgroup of CD44+/CD24+ cells as well as the tumor stemness of pancreatic cancer." (PMID 37743465, 2023). "The results revealed that MG132 restored the expression of CDK1 in pancreatic cancer cells with treatment of fisetin." (PMID 37743465, 2023). "To further determine the role of CDK1 in pancreatic cancer in vivo, we constructed wild type and CDK1-silenced nude mice xenograft models." (PMID 37743465, 2023). "In this study, we demonstrated that CDK1 was correlated with prognosis and was highly expressed in pancreatic cancer tissue and gemcitabine-resistant cells." (PMID 37743465, 2023). "In this study, we focused on the specific role of CDK1 in pancreatic cancer cells and its CSC subpopulation." (PMID 37743465, 2023). "Mutation or acetylation of CDK1 at K33 weakened STAT3 phosphorylation at Y705, impairing the expression of stem-related genes and pancreatic cancer stemness." (PMID 37743465, 2023). "Our findings demonstrate that ASPP2 is phosphorylated by CDK1 at S562 and S704 during mitosis and is required for pancreatic cancer cell proliferation in vitro and in vivo." (PMID 38001686, 2023). "Recent studies have shown that several protein kinases, like cyclin-dependent kinase 1 (CDK1), play a significant role in pancreatic cancer resistance by modifying proteins involved in key signaling pathways." (PMID 36979869, 2023). "In line with our results, CDK1 was one of the 20 key hub genes related to pancreatic cancer metastasis and prognosis." (PMID 37185598, 2023). "Acetylation of CDK1 at K33 reduces pancreatic cancer stemness by inhibiting the phosphorylation of STAT3." (PMID 37743465, 2023). "Considering that CDK1 is a typical cell cycle regulator and has promoted the progression of pancreatic cancer." (PMID 35927248, 2022). "We also specifically investigated the expression of the CDK1 gene in highly prevalent malignancies such as lung, gastric, liver, colon, breast, esophageal, and pancreatic cancers." (PMID 36090896, 2022). "Taken together, these data suggested that ZNF655 facilitated malignant behaviors of pancreatic cancer cells via promoting the binding of E2F1 to CDK1 promoter." (PMID 35927248, 2022). "To date, C646 has been documented to transcriptionally repress tumor formation in breast and pancreatic cancer growth by suppressing cyclin B1 and CDK1." (PMID 35205642, 2022). "ASPM, CCNB1, CDK1, MELK, OAS3, PPTG1 and TOP2A were thought to be significantly associated with shorter overall survival in pancreatic cancer patients." (PMID 36167975, 2022).
pancreatic cancer (continued). "Mechanically, these data suggested that ZNF655 facilitated malignant behaviors of pancreatic cancer cells via promoting the binding of E2F1 to CDK1 promoter." (PMID 35927248, 2022). "Recently, it has been reported that that CDK1 is a typical cell cycle regulator and has promoted the progression of pancreatic cancer." (PMID 35927248, 2022). "The promotive role of ZNF655 in pancreatic cancer via CDK1 was determined, which drew further interest regarding its clinical application as a promising therapeutic target." (PMID 35927248, 2022). "TOP2A and CDK1 are cell cycle-related genes and they facilitate proliferation and invasion of pancreatic cancer." (PMID 33748143, 2021). "Cyclin-dependent kinase 1 (CDK1) is a stimulator of cell cycle progression and its activity is regularly enhanced in pancreatic cancer cells." (PMID 34503199, 2021). "Surprisingly, clinicopathological analysis indicated the strong correlation between CDK1 expression and hTERT T249 phosphorylation in pancreatic cancer (p = 0.0289)." (PMID 32214089, 2020). "We confirmed that the same pancreatic cancer cells were co-stained with anti-CDK1 and TpMab-1 by immunofluorescence images." (PMID 32214089, 2020). "In one study, CDK1 inhibitors contributed to a marked reduction in the proportion of cells in S and G2/M phases of the cell cycle in PDAC tumor cell models; targetting CDK1 also showed promising anticancer activity in pancreatic cancer cells." (PMID 30765611, 2019). "In this study, Spiclomazine arrests the cell cycle by inhibiting the expression levels of Cyclin B1 and CDK1 involved in G2 phase in these pancreatic cancer cell lines." (PMID 29467941, 2018). "In pancreatic cancer, it was also observed that CDK1 can phosphorylate Vgll4, which in consequence activates the Hippo and Wnt pathways." (PMID 29903985, 2018). "In addition, it was found that CDK1/2/5/9 inhibition overcomes IFNγ-mediated adaptive immune resistance in pancreatic cancer." (PMID 40264756, 2025). "Based on previous investigations highlighting the significance of CDK1 in maintaining stem cell pluripotency, we hypothesized that CDK1 was related to PCSC function in pancreatic cancer." (PMID 37743465, 2023). "Furthermore, a previous report indicating the role of DEPDC1B in pancreatic cancer development through targeting the Akt/Gsk3b/Snail pathway also provides support for the alleviation of DEPDC1B overexpression-induced effects by CDK1 knockdown." (PMID 36568241, 2022). "Functional recovery experiments were conducted to clarify whether there was a synergistic effect between ZNF655 and CDK1 in pancreatic cancer." (PMID 35927248, 2022). "Additionally, the mRNA expression level of CDK1 in pancreatic cancer cell lines PANC-1 and SW1990 was significantly higher than that of normal pancreatic cell line HPDE6-C7." (PMID 35927248, 2022). "Furthermore, knockdown of CDK1 alleviated the promoting effects of ZNF655 overexpression in pancreatic cancer cells." (PMID 35927248, 2022). "ZNF655 facilitated malignant behaviors of pancreatic cancer cells via promoting the binding of E2F1 to CDK1 promoter, which may contribute to the development of promising targets for tumor diagnosis and treatment." (PMID 35927248, 2022). "Consistently, the expression of CDK1 in pancreatic cancer tissues was higher than that in adjacent normal tissues, suggesting that CDK1 may exhibit an important role in pancreatic cancer." (PMID 35927248, 2022). "Additionally, knockdown of CDK1 alleviated the promoting effects of ZNF655 overexpression in pancreatic cancer cells." (PMID 35927248, 2022). "As a consequence, ZNF655 promoted the malignant behavior of pancreatic cancer cells through CDK1." (PMID 35927248, 2022). "Inhibition of the kinase activity of CDK1 can prevents the expression of relevant immune checkpoints, alters the tumor microenvironment, and can significantly improve the overall survival rate in a mouse pancreatic cancer tumor model." (PMID 36090896, 2022).
pancreatic cancer (continued). "Moreover, inhibition of CDC25, an activator of CDK1, leads to a reduction in growth of pancreatic cancer cell lines." (PMID 34503199, 2021). "Wee1 inhibition by adavosertib has been shown to reduce p-CDK1 (Tyr15) levels in pancreatic tumors." (PMID 34298699, 2021). "Thus, there is limited research suggesting that CDK1 inhibition induces differentiation of pancreatic cancer stem cells." (PMID 34503199, 2021). "CDK1 regulation of this checkpoint is a key tumorigenic event, and it has been shown that the G2M pathway-related genes are a potential therapeutic target in pancreatic cancer." (PMID 33036243, 2020). "We also found strong staining with anti-CDK1 pAbs in pancreatic cancer cells." (PMID 32214089, 2020). "To further investigate the molecular mechanism of Spiclomazine-induced cell cycle arrest, we evaluated the effect of Spiclomazine on the expression levels of Cyclin B1 and CDK1 involved in G2 phase in these pancreatic cancer cell lines for 24 hours using WB assay." (PMID 29467941, 2018). "Whether CDK1/cyclin B expression/activity is increased in pancreatic cancer remains to be determined." (PMID 26440309, 2015). "Thus, we speculated that CDK1 might activate STAT3 via its kinase function to influence the maintenance of cancer stemness in pancreatic cancer." (PMID 37743465, 2023). "In addition, CDK1 and EGFR were significantly associated with the OS of pancreatic cancer." (PMID 34957301, 2021). "PPP2R1A, a well-characterized scaffold subunit of the PP2A complex, has been reported to decrease the cytotoxicity of chemoradiation treatment in pancreatic cancer via activating HRR and inhibiting CDC25/and CDK1." (PMID 38654331, 2024). "KEGG and GO enrichment analysis revealed that cell cycle signaling pathway was significantly different in gemcitabine-resistant human pancreatic cancer PANC-1 cells, among which CDK1 was highly expressed in drug-resistant cells." (PMID 37743465, 2023). "Some of them (ITGA3, CDK1, IFIT3, ANXA1, ANXA2, OAS1, and LACTB) have been studied to varying degrees concerning their relationship with pancreatic cancer." (PMID 36834681, 2023). "Silencing of MELK significantly reduces pancreatic cancer development, as MELK promotes CDK1 involvement in the cell cycle and cell progression in cancers." (PMID 38144520, 2023). "In the pancreatic cancer tissues, we confirmed that protein levels of LARP7, CDK1, and CCNB1 increased notably in tumor tissues compared with non-tumor tissues." (PMID 36434634, 2022). "Consistently, ERBB2 knockdown also decreased cyclin A, cyclin B, CDK1, and CDK2 protein contents in both pancreatic tumor cells." (PMID 35343383, 2022). "The downstream mechanism of ZNF655 regulating pancreatic cancer progression was preliminarily investigated and found that knockdown of ZNF655 downregulated CDK1." (PMID 35927248, 2022). "Seven GRGs: CDK1, DSC2, MET, PYGL, CHST12, ERO1A, and SLC35A3 were selected to construct the prognostic model related to the overall survival rate of patients with pancreatic cancer." (PMID 33912561, 2021). "Expression analysis further revealed that CDK1, DSC2, ERO1A, MET, PYGL, and SLC35A3 were highly expressed in pancreatic cancer while CHST12 was highly expressed in normal pancreatic tissues." (PMID 33912561, 2021). "Another study showed that treatment of human pancreatic cancer cell lines with the HDAC inhibitor TSA and the flavonoid silibinin led to a downregulation of Bcl-xL, which was accompanied by inhibition of CDK1." (PMID 34503199, 2021). "The phosphorylation of DRP1 at serine 616, which activates GTPase activity, is mediated by CDK1 in HeLa cells and is regulated by ERK in pancreatic cancer cell lines." (PMID 33152171, 2021). "Eight genes (BUB1, BUB1B, CCNA2, CCNB2, CDC6, CDC20, CDK1, and TTK) among 21 common network genes were correlated with worse survival of pancreatic cancer, highlighted with P-value significantly <0.05." (PMID 32117719, 2020).